IKBKGP1 (inhibitor of nuclear factor kappa B kinase subunit gamma pseudogene 1)
Synonyms: deltaNEMO; IKBKGP
Gene: Transcribed unprocessed pseudogene on chromosome X (154,639,978 to 154,648,275, reverse strand). Ensembl gene ENSG00000275882.
Diseases named in the same sentence as IKBKGP1 in open-access papers:
IKBKGP1 is named in the same sentence as 1 disease in open-access papers, as found by Europe PMC text mining. Sharing a sentence is not in itself a finding about the gene and the disease.
IKBKGP1 shares sentences with these, for which no sentence is quoted: migraine (1 paper).